LINC02695 (long independently transcribed non-coding RNA 2695)
Gene: Long non-coding RNA gene on chromosome 11 (86,191,468 to 86,193,683, reverse strand). Ensembl gene ENSG00000254699.
Diseases named in the same sentence as LINC02695 in open-access papers:
LINC02695 is named in the same sentence as 1 disease in open-access papers, as found by Europe PMC text mining. Sharing a sentence is not in itself a finding about the gene and the disease.
LINC02695 shares sentences with these, for which no sentence is quoted: Huntington disease (1 paper).